RNU6-469P (RNA, U6 small nuclear 469, pseudogene)
Gene: Small nuclear RNA gene on chromosome 4 (84,886,386 to 84,886,486, reverse strand). Ensembl gene ENSG00000252062.
Homologues: Orthologues: chimpanzee U6 (99% identical), macaque U6 (90% identical), rabbit U6 (69% identical), dog U6 (61% identical), mouse Gm55756 (61% identical), guinea pig U6 (60% identical), pig U6 (58% identical), tropical clawed frog U6 (58% identical), rat LOC120094411 (57% identical), mouse Gm25886 (55% identical), guinea pig U6 (54% identical), zebrafish U6 (37% identical). Paralogues in human: RNU6-704P (75% identical), RNU6-831P (75% identical), RNU6-1331P (74% identical), RNU6-590P (74% identical), RNU6-744P (74% identical), RNU6-1060P (73% identical), RNU6-10P (73% identical), RNU6-1209P (73% identical), RNU6-15P (73% identical), RNU6-183P (73% identical), RNU6-196P (73% identical), RNU6-378P (73% identical), and 1284 more.